LPCAT3 (lysophosphatidylcholine acyltransferase 3)
Diseases named in the same sentence as LPCAT3 in open-access papers (continued):
Sharing a sentence is not in itself a finding about the gene and the disease.
Insulin resistance (5 papers, 2022 to 2025). Increased resistance towards insulin, that is, diminished effectiveness of insulin in reducing blood glucose levels. "Loss of Lpcat3 in the liver improves insulin resistance and blunts lipogenesis in both HFD‐fed and genetic ob/ob mouse models." (PMID 37088778, 2023). "Elevated activity and expression of LPCAT3 have also been noted in animal models exhibiting insulin resistance." (PMID 40737292, 2025). "In general, most studies support the idea that inhibiting LPCAT3 offers benefits in strengthening insulin signaling, alleviating insulin resistance, and improving glucose tolerance." (PMID 40737292, 2025). "Taken together, these data indicate that Lpcat3 deficiency improves both hyperglycemia and hypertriglyceridemia in HFD‐induced insulin resistance." (PMID 37088778, 2023). "Under insulin resistance, hyperinsulinemia leads to an excessive increase in Lpcat3 expression and membrane unsaturation, which enhances lipogenesis and VLDL secretion, resulting in hypertriglyceridemia." (PMID 37088778, 2023). "To further assess the involvement of LPCAT3 activity in the pathogenesis of insulin resistance, we crossed LKO mice with ob/ob mice to generate ob/ob, Lpcat3fl/fl, Cre‐ (OB) and ob/ob, Lpcat3fl/fl, Cre+ (OLKO) mice." (PMID 37088778, 2023). "In conclusion, our study unveils LPCAT3 as a novel mediator of reciprocal regulation between phospholipid remodeling and insulin signaling that contributes to the pathogenesis of insulin resistance." (PMID 37088778, 2023). "For instance, in patients with T2DM, persistent hyperglycemia and insulin resistance may trigger certain compensatory mechanisms, ultimately affecting the expression or activity of LPCAT3." (PMID 40737292, 2025). "However, LPCAT3 is important in the development of insulin resistance and in some cancers." (PMID 38893234, 2024). "And experimental studies at the animal-level have found several clues linking phospholipid metabolism to insulin resistance through the knockout of phospholipid synthesis enzymes, like phosphatidylethanolamine N-methyltransferase (PEMT) and lysophosphatidylcholine acyltransferase 3 (LPCAT3)." (PMID 38674894, 2024). "Next, we examined if LPCAT3 and PL remodeling play any roles in HFD‐induced insulin resistance." (PMID 37088778, 2023).
diabetes (4 papers, 2021 to 2025). "This study aimed to explore the role of serum lysophosphatidylcholine acyltransferase 3 (LPCAT3) in glucose and lipid metabolism and its association with type 2 diabetes mellitus (T2DM)." (PMID 40737292, 2025). "Furthermore, diabetes upregulates lysophosphatidylcholine acyltransferase-3 (LPCAT3), facilitating the integration of polyunsaturated fatty acids (PUFA) into phospholipid membranes, and downregulates acyl-CoA thioesterase-1 (ACOT1), which further promotes ferroptosis." (PMID 38824159, 2024). "However, we are currently unsure whether there is a direct link between LPCAT3 and the development of diabetes, and this needs to be further investigated." (PMID 35711841, 2022).
Glucose intolerance (4 papers, 2021 to 2024). Glucose intolerance (GI) can be defined as dysglycemia that comprises both prediabetes and diabetes. "The overexpression of skeletal muscle-specific LPCAT3 is sufficient to enhance HFD-feeding-induced glucose intolerance in mice." (PMID 35711841, 2022). "Conversely, skeletal muscle-specific overexpression of LPCAT3 (LPCAT3-MKI) promoted glucose intolerance." (PMID 34262459, 2021). "In addition, LPCAT3 overexpression in skeletal muscle impairs insulin signaling and aggravates glucose intolerance." (PMID 38519981, 2024). "However, LPCAT3 overexpression in skeletal muscle exacerbates glucose intolerance, and the inhibition of its expression enhances insulin signaling and improves insulin sensitivity, thereby improving insulin resistance." (PMID 35711841, 2022).
Hyperglycemia (4 papers, 2016 to 2025). An increased concentration of glucose in the blood. "Postprandial glucose tolerance tests after feeding these animals with a bolus lipid-glucose mixed meal revealed that LPCAT3 overexpression improved postprandial hyperglycemia and glucose tolerance compared with control mice with LacZ adenovirus injection." (PMID 27110687, 2016).
hyperuricemia (4 papers, 2023 to 2025). An abnormally high level of uric acid. "Additionally, it has also been suggested that alteration in lysophosphatidylcholine metabolism during hyperuricemia might be caused by the upregulation of the lysophosphatidylcholine acyltransferase 3 enzyme (LPCAT3, EC 2.3.1.23)." (PMID 38042879, 2023). "Based on our data and in concordance with previous publications, the increased LPCAT3 activity induced by increased levels of UA appears to be important in the pathobiochemistry of lipids in hyperuricemia and gout." (PMID 38042879, 2023). "At the molecular level, studies further demonstrate that hyperuricemia induces oxidative stress, endothelial dysfunction, and systemic inflammation, with hepatic LPCAT3 and CXCL‐13 upregulation driving lipid disturbances, characterized by elevated triglycerides and LDL‐C and reduced HDL‐C." (PMID 41287972, 2025). "It is suggested that LPCAT3 may be a key regulator linking hyperuricemia and disorders of lipid metabolism." (PMID 41322694, 2025). "Our data suggest that regulating LPCAT3 could serve as a new therapeutic target for hyperuricemia and gout in the future and should be the focus of further studies." (PMID 38042879, 2023). "In a previous study, we found that high uric acid (UA) induced lipid disturbances mediated via lysophosphatidylcholine acyltransferase 3 (LPCAT3) upregulation in the liver, with hepatic damage observed in diet‐induced hyperuricemia model." (PMID 37502610, 2023).
colon cancer (3 papers, 2021 to 2024). "It lowered pro-inflammatory cytokine levels of IL-1β and TNF-α and enhanced carnitine palmitoyl transferase 1A (CPT1A) and lysophosphatidylcholine acyltransferase 3 (LPCAT3), thereby attenuating the anti-proliferative effect of SIN (2.5 mM) on human colon cancer cells (HT-29, HCT-116, and SW-480)." (PMID 38276618, 2024).
osteoarthritis (3 papers, 2020 to 2024). A noninflammatory degenerative joint disease occurring chiefly in older persons, characterized by degeneration of the articular cartilage, hypertrophy of bone at the margins and changes in the synovial membrane. "It has been reported that LPCAT3 was upregulated in OA and contributes to the ferroptosis of chondrocytes in osteoarthritis." (PMID 38519981, 2024). "This is the first study that establishes the role of MALT1-LPCAT3 axis in the development of osteoarthritis and provides novel therapeutic avenues targeting this pathway using LPCAT3 siRNA-lipid nanoparticle approach or local injections of MALT1-inhibitors for the treatment of OA." (PMID 38519981, 2024). "This is the first study to describe the role of the MALT-LPCAT3 axis in the development of osteoarthritis.Our data supports that targeting the MALT1-LPCAT3 axis using MALT1 inhibitors or LPCAT3 siRNA-liposomes may become attractive therapies for the treatment of OA." (PMID 38519981, 2024).
acute kidney injury (2 papers, 2023 to 2025). Sudden and sustained deterioration of the kidney function characterized by decreased glomerular filtration rate, increased serum creatinine or oliguria. "Overexpression of LPCAT3 in renal tubular epithelial cells leads to decreased cell viability and ferroptosis induction, and elevated LPCAT3 expression in the blood during acute kidney injury models underscores its potential involvement in kidney injury progression." (PMID 40737292, 2025). "Gpx4 knockout triggers acute renal failure in mice which can be rescued by ACSL4 inhibitors, whereas Lpcat3 knockout is also lethal in vivo, likely because LPCAT3 is essential for membrane phospholipid composition, triglyceride transport, and lipoprotein production." (PMID 38007476, 2023).
Hypertension (2 papers, 2024 to 2025). The presence of chronic increased pressure in the systemic arterial system. "In mice with high-salt-induced hypertension, there was a significant increase in the protein and mRNA expression of ACSL4 and LPCAT3, along with a decrease in GPX4 expression (p < 0.001)." (PMID 41019540, 2025). "In summary, our study preliminarily showed that hypertension induces intracellular PUFAs to bind to phospholipids under the catalysis of ACSL4 and LPCAT3 to form PL–PUFAs, which are further oxidized by ALOX15, resulting in the accumulation of lipid peroxides." (PMID 39595632, 2024).
intestinal tumor (2 papers, 2022 to 2024). "Existing studies have found that LPCAT3 is closely associated with intestinal stem cell proliferation and the development of intestinal tumors." (PMID 35711841, 2022). "Thus, we suggest that intestinal LPCAT3 deficiency is likely due to the promotion of cholesterol production, which induces excessive ISC proliferation and further promotes intestinal tumor formation." (PMID 35711841, 2022).
lung adenocarcinoma (2 papers, 2025). A carcinoma that arises from the lung and is characterized by the presence of malignant glandular epithelial cells. "In addition to ACSL3, ACSL4 has been shown to co-regulate ferroptosis in lung adenocarcinoma in conjunction with lysophosphatidylcholine acyltransferase 3 (LPCAT3) and yes-associated protein (YAP)." (PMID 41288931, 2025). "LPCAT3/ACSL4 knockout can protect lung adenocarcinoma cells from ferroptosis, while ectopic expression of LPCAT3 and ACSL4 has the opposite effect." (PMID 40724837, 2025).
lung carcinoma (2 papers, 2023 to 2024). "Targeting the Lands Cycle through lysophosphatidylcholine acyltransferase 3 (LPCAT3) or phospholipase A2 group IVC (PLA2G4C) inhibition resulted in increased ferroptosis, indicating that proper functioning of the Lands Cycle is necessary to prevent cell death in KRAS-mutant lung cancer." (PMID 37779896, 2023).
ovarian carcinoma (2 papers, 2015 to 2021). A malignant neoplasm originating from the surface ovarian epithelium. "Meanwhile, we constructed a novel prognostic signature consisting of three FRGs (HIC1, LPCAT3, DUOX1), The three FRG-based risk score model was capable of distinguishing ovarian cancer patients with significantly different outcomes, and the risk score was the independent prognostic factor." (PMID 35071242, 2021).
steatosis (2 papers, 2021). Increased lipid within the cytoplasm of cells. "Mboat7 and Lpcat3 LSKO mice have similar phenotypes but differ in that Lpcat3 LSKO mice also have reduced TG-rich lipoprotein secretion rates, resulting in steatosis." (PMID 32859645, 2021). "In the present study, we further demonstrated that KP can modulate the mRNA or the protein expression of the molecules involved in LXRα-LPCAT3-ERS pathway in both HFD-induced mice model and PA/OA-induced steatosis cell model." (PMID 34262459, 2021).
viral infection (2 papers, 2023 to 2024). "In this case, Mpro-induced LPCAT3 cleavage might lead to or aggravate gastrointestinal symptoms during viral infection." (PMID 37632038, 2023).
acute myeloid leukemia (1 paper, 2023). Acute myeloid leukemia (AML) is a group of neoplasms arising from precursor cells committed to the myeloid cell-line differentiation. "For instance, LPCAT3 was correlated with immune infiltration in acute myeloid leukemia." (PMID 37294538, 2023).
Alzheimer disease (1 paper, 2020). A progressive, neurodegenerative disease characterized by loss of function and death of nerve cells in several areas of the brain leading to loss of cognitive function such as memory and language. "Lpcat3, a gene we found to have reduced expression in GPe PV+ neurons on DD, is necessary for ferroptosis, which has been linked to neurodegeneration in PD and Alzheimer's disease." (PMID 33188066, 2020).
colitis (1 paper, 2025). Inflammation of the colon. "Interestingly, IHC staining results revealed that, except for TXNRD1, the expression levels of ACSL4 and LPCAT3 in colitis mice were higher than those in the normal control group, while SLC7A11 and GPX4 displayed the opposite consequence." (PMID 40691131, 2025).
gestational diabetes (1 paper, 2025). Carbohydrate intolerance first diagnosed during pregnancy. "Ferroptosis and gestational diabetes mellitus (GDM) converge at multiple molecular intersections, notably through the involvement of key regulatory genes including GPX4, SLC7A11, ACSL4, and LPCAT3." (PMID 41020807, 2025).
heart failure (1 paper, 2025). Inability of the heart to pump blood at an adequate rate to meet tissue metabolic requirements. "LPCAT3 expression demonstrated low diagnostic accuracy for heart failure (AUC = 0.696)." (PMID 40672390, 2025).
Hypercholesterolemia (1 paper, 2025). An increased concentration of cholesterol in the blood. "We investigated whether an alteration of the PUFA homeostasis triggered by a combined Lpcat3/Elovl5 deficiency in macrophages would affect the atherosclerotic process in a mouse model of hypercholesterolemia." (PMID 40345182, 2025).
Hyperinsulinemia (1 paper, 2023). An increased concentration of insulin in the blood. "Hyperinsulinemia induced by high‐fat diet (HFD) feeding augments hepatic Lpcat3 expression and membrane unsaturation." (PMID 37088778, 2023).
intestinal cancer (1 paper, 2020). "Meanwhile, excess cholesterol can inactive lysophosphatidylcholine acyltransferase 3 (Lpcat3), which is responsible for polyunsaturated phospholipid synthesis and drives stem cell proliferation in intestinal cancer in vivo and ex vivo." (PMID 32486083, 2020).
ischemic stroke (1 paper, 2025). A stroke disorder caused by obstruction of blood flow to the brain, due to thrombotic (local blood clot formation) or embolic (due to a blood clot or other material traveling from another site) event. "Our analysis revealed a significant negative causal effect of LPCAT3 expression in human whole blood on the risk of ischemic stroke, indicating that higher LPCAT3 expression is associated with a reduced likelihood of ischemic stroke." (PMID 40345182, 2025). "Additionally, Mendelian randomization analysis supports a causal relationship between LPCAT3 expression and reduced risk of ischemic stroke." (PMID 40345182, 2025). "Additionally, Mendelian randomization analysis supports a protective role for LPCAT3, showing that higher LPCAT3 expression in human whole blood is causally linked to a reduced risk of ischemic stroke." (PMID 40345182, 2025). "Furthermore, we performed Mendelian randomization analysis to explore the potential causal relationship between the expression levels of LPCAT3 and ELOVL5 and the incidence of ischemic stroke in humans." (PMID 40345182, 2025).
liver fibrosis (1 paper, 2022). "The activity of the SCAP/SREBP/LPCAT3 axis was found to be inversely associated with liver fibrosis severity in human NASH." (PMID 35380992, 2022).
malnutrition (1 paper, 2020). Inadequate nutrition resulting from poor diet, malabsorption, or abnormal nutrient distribution. "The reduction of ARA-PLs by genetic deletion of Lpcat3 led to neonatal lethality because of malnutrition triggered by the failure of lipoprotein formation." (PMID 32891885, 2020).
nephrotic syndrome (1 paper, 2025). A collection of symptoms that include severe edema, proteinuria, and hypoalbuminemia; it is indicative of renal dysfunction. "In the Nephrotic Syndrome Study Network (NEPTUNE) database, LPCAT3, ELOVL7 and FADS2 were all negatively associated with eGFR and positively associated with creatine and urea nitrogen." (PMID 41285716, 2025).
pancreatic cancer (1 paper, 2021).
pancreatic tumors (1 paper, 2021). "Moreover, we showed that correlations between expressions of FTH1 and the ferroptosis regulators, FDFT1 and LPCAT3, may be linked to initiation of pancreatic tumors." (PMID 34711879, 2021).
Pneumocystis infection (1 paper, 2023). "We next validated the expression of Lpcat3 and Nr1h3 in the DEX-treated or untreated mice lungs at 2 weeks post Pneumocystis infection using qPCR." (PMID 37359523, 2023).
prostatitis (1 paper, 2022). An infectious or non-infectious inflammatory process affecting the prostate gland. "In this study, the inactivation of the system Xc−/GPX4 axis, accumulation of iron, and activation of ACSL4/LPCAT3 axis strongly highlighted the important role of ferroptosis on prostatitis development." (PMID 35755168, 2022). "Moreover, elevated iron concentration and differential expression of ferroptosis indicators, including GPX4, SLC7A11/Xc−, ACSL4, LPCAT3, and PTGS2, implied that ferroptosis engaged in the development of prostatitis in the context of iron overload and oxidative damage." (PMID 35755168, 2022).
sarcopenia (1 paper, 2025). Progressive decline in muscle mass due to aging which results in decreased functional capacity of muscles. "LPCAT3 inhibition reduces lipid hydroperoxides and alleviates muscle atrophy, suggesting a potential target for sarcopenia therapy." (PMID 39963429, 2025). "In skeletal muscle-specific LPCAT3 knockout mice, lipid hydroperoxide levels were significantly reduced, indicating that suppressing the Lands cycle may be an effective strategy for alleviating sarcopenia." (PMID 39963429, 2025).
subarachnoid hemorrhage (1 paper, 2025). A serious neurological disorder characterized by intracranial hemorrhage into the subarachnoid space. "LPCAT3 is also involved in subarachnoid hemorrhage induced early brain injury and associated with ferroptosis through suppress and upregulate LPCAT3 expression level." (PMID 40744916, 2025).